APOB (apolipoprotein B)
Diseases named in the same sentence as APOB in open-access papers (continued):
Sharing a sentence is not in itself a finding about the gene and the disease.
Obesity (continued). "Important contributors to the residual correlation when considering common cardiovascular disease exposures are molecular pathways, which are not accounted for when considering traits like ApoB or obesity." (PMID 37419091, 2023). "Obesity is often accompanied by high levels of total cholesterol, TG, LDL, ultra-low-density lipoprotein (ULDL), and lipoproteins, as well as decreased levels of HDL and apolipoprotein B (ApoB)." (PMID 35514987, 2022). "In our study, the ApoB/ApoA1 ratio was significantly correlated with WC, TG, HDL, SBP, and FPG, but not with DBP, and the association was independent of age or obesity." (PMID 35069437, 2021). "Our results also showed positive associations between the ApoB/ApoA1 ratio and ALT and AST regardless of age and obesity, which is consistent with previous reports." (PMID 35069437, 2021). "Although apolipoprotein B100 (ApoB100) plays a key role in peripheral fat deposition, it is not considered a suitable therapeutic target in obesity." (PMID 26519425, 2016). "The SNPs of ABCA-1 (LDL-C and ApoA1/ApoB); LIPC (TC, LDL-C, ApoA1 and ApoB); LIPG (ApoB); MTHFR (TC, TG and LDL-C); MYLIP (TC and TG); PCSK9 (TG, HDL-C, ApoB and ApoA1/ApoB); PPARD (TG and ApoA1/ApoB); and SCARB1 (TG, ApoA1 and ApoB) interacted with overweight/obesity to modulate serum lipid levels." (PMID 23039238, 2012). "In addition, our study is the first to demonstrate a positive correlation between obesity and anti-ApoB IgG levels, while previous studies have proposed a negative association with metabolic risk factors." (PMID 35479271, 2022). "In addition, participants with obesity at the initial assessment had significantly higher ALT, triglycerides, and ApoB concentrations than overweight and normal-BMI participants at the initial assessment and this difference disappeared at the annual assessment." (PMID 34444842, 2021). "In the present study, we postulated that a similar immunization approach may reveal or unleash obesity-related roles of ApoB(s) that were not, or cannot be, revealed or unleashed by the genetic approach." (PMID 26519425, 2016). "Participants categorized as having preclinical obesity exhibited significantly higher levels of LDL cholesterol and apolipoprotein B compared to non-obese peers." (PMID 40487022, 2025). "High levels of serum triglycerides, free fatty acids, very low-density lipoproteins (VLDL), apolipoprotein B (Apo B), and non-high-density lipoprotein (non-HDL) cholesterol are typical obesity-related lipid abnormalities." (PMID 35945482, 2022). "ApoB and/or non-HDL-C concentrations reflect the atherogenic lipid burden more accurately than LDL-C alone in obesity and should be used as treatment targets." (PMID 23584084, 2013). "We have utilized mice overexpressing a full length human apoB transgene and mice lacking cardiac expression of MTP-A to explore the role of cardiac lipoprotein formation on lipid metabolism and heart function in mice with diet-induced obesity." (PMID 19390571, 2009). "In addition, four peptides derived from the ATP binding cassette subfamily A member 1 (ABCA1), apolipoprotein B (APOB), and cAMP response element-binding protein (CREB) showed potential in the treatment of obesity; however, they were not pharmacologically analyzed." (PMID 32121443, 2020).
Insulin resistance (226 papers, 2007 to 2026). Increased resistance towards insulin, that is, diminished effectiveness of insulin in reducing blood glucose levels. "In the context of MAFLD, insulin resistance is linked to increased ApoB expression and delayed ApoB clearance." (PMID 38393015, 2024). "Outside pregnancy, insulin resistance has been related to LDL particle concentrations, and in a cross-sectional design the apoB-to-ApoA1 ratio has been associated with insulin resistance." (PMID 36979405, 2023). "Accordingly, the associations between insulin resistance, ApoB, and ApoA1 resembled the associations between insulin resistance, LDL particle concentration, and HDL particle concentration, respectively." (PMID 36979405, 2023). "Several studies observed that APOB/ApoA1 was significantly associated with higher odds of MetS and insulin resistance in Chinese population and PCOS patients." (PMID 35909551, 2022). "Logistic regression analyses were used to evaluate the relationships between APOA-I/APOB genetic polymorphisms, insulin resistance, and MetS in OSA." (PMID 33005209, 2020). "Many clinical trials have revealed that APOA-I and APOB are independently associated with insulin resistance and MetS." (PMID 33005209, 2020). "In our study cumulative APOA-I genetic variations (APOA-I GRS) decreased the risk of insulin resistance and MetS, whereas cumulative APOB genetic variations (APOB GRS) increased the risk of MetS in OSA." (PMID 33005209, 2020). "Insulin resistance, measured as the homeostasis index (HOMA-IR) and the fasting insulin level, correlated with apoB, with the apoB : apoA-I ratio, and inversely with apoA-I supporting known association of insulin resistance with lipoprotein transport." (PMID 28473926, 2017). "First, data from animal studies have provided evidence that insulin resistance is associated with a reduction in ApoB degradation in hepatocytes, leading to an increase in the ApoB pool available for VLDL assembly." (PMID 25725623, 2015). "The aim of our study was to assess the association between insulin resistance and apolipoprotein B/apolipoprotein A-I ratio, MetS components, total cholesterol (TC), and low-density lipoprotein cholesterol (LDL-C) in the population of Georgia." (PMID 24949011, 2014). "Low HDL and high apoB/apoA-I ratio is associated with obesity, metabolic syndrome, insulin resistance, and NAFLD." (PMID 23554788, 2013). "Among men, abdominal obesity was associated with increasing age, insulin resistance, lower apoA1, and higher apoB levels." (PMID 21159215, 2011). "In general, SAD was a stronger predictor of cardiovascular risk factors, especially of insulin resistance, apoB, insulin, triglycerides and CRP, than the other anthropometric measures." (PMID 17391519, 2007). "Association of apolipoprotein B (Apo-B) with insulin resistance (log HOMA-IR)." (PMID 40642688, 2025). "Association of apolipoprotein B (Apo-B) with insulin resistance*." (PMID 40642688, 2025). "Observational studies found that the ApoB/ApoA1 ratio was significantly associated with insulin resistance in non-diabetic subjects and could become an independent predictor of insulin resistance." (PMID 38310324, 2024). "In addition, six loci were linked to insulin resistance, type 2 diabetes, or reduction in HbA1c levels in type 2 diabetes (APOB, HPR, TM6SF2, KSR2, JMJD1C, and SLCO1B1)." (PMID 38532495, 2024). "Additionally, hyperinsulinemia and insulin resistance are associated with an increased free fatty-acid release promoting high triglycerides levels, high levels of ApoB and VLDL, and a low high-density lipoprotein (HDL) cholesterol level." (PMID 35458670, 2022). "Dysregulation of ApoB metabolism can consequently cause insulin resistance." (PMID 33794863, 2021). "ApoB levels are closely associated with fat accumulation in the liver and insulin resistance." (PMID 32527258, 2020).
Insulin resistance (continued). "We aimed to evaluate whether the multiple single nucleotide polymorphism (SNP) variants of APOA-I and APOB exert a collaborative effect on insulin resistance and MetS in OSA." (PMID 33005209, 2020). "Another study reported that insulin resistance was associated with the serum ApoB levels." (PMID 27111895, 2016). "Insulin resistance states have been associated with oxidized low-density lipoproteins in Latino individuals, elevated levels of apoB, and higher lipoprotein insulin resistance index suggesting association with lipoprotein particle size and cardiovascular risk and vascular markers of inflammation." (PMID 27379332, 2014). "The ApoB/ApoA1 ratio is strongly associated with insulin resistance." (PMID 24093822, 2013). "Waist circumference and the ratio of apolipoprotein B to apolipoprotein A-I (ApoB/ApoA-I ratio) had the highest odds ratio (OR) in increasing the risk of insulin resistance and NAFLD, whereas cardiorespiratory fitness, followed by healthy eating index, decreased this risk significantly." (PMID 22224077, 2011). "Similarly, the level of ApoA1 corresponds to the quantity of HDL particles; therefore, apolipoproteins taken individually or the ratio of ApoB and ApoA1 (ApoB/A1 ratio) would theoretically serve as optimal markers of lipid abnormalities associated with insulin resistance and MetS." (PMID 37420190, 2023). "ApoB may be useful in predicting CVD risk in states of insulin resistance." (PMID 36678541, 2022). "Interestingly, recent studies have suggested that abnormalities in triglyceride-rich apolipoprotein B (apoB)-containing lipoproteins may precede insulin resistance, which in turn is a major risk factor for T2D development." (PMID 34321006, 2021). "However, whether APOA-I and APOB are independently associated with insulin resistance and MetS in OSA remains uncertain." (PMID 33005209, 2020). "However, the relationships between the cumulative effects of multiple genetic variants of APOA-I, APOB, insulin resistance, and MetS in OSA remain unclear." (PMID 33005209, 2020). "Therefore, insulin deficiency or hepatic insulin resistance may increase the secretion of apoB, and upregulate VLDL and LDL and increase cardiovascular risk." (PMID 29975702, 2018). "The HTGW phenotype, meanwhile, serves as a practical clinical marker for a cluster of metabolic disturbances such as hyperinsulinemia, elevated apolipoprotein B (Apo B), and high LDL cholesterol frequently associated with insulin resistance." (PMID 41292675, 2025). "Many of these genes, including APOB, INSR, and PPARG, have multiple sources of supporting evidence and are implicated in known MASLD mechanisms like lipid metabolism, insulin resistance, and adiposity." (PMID 40065360, 2025). "Insulin resistance (IR) and related metabolic abnormalities drive a pathological increase in ApoB particle number." (PMID 41346943, 2025). "Since we have also shown that HSD causes glial insulin resistance, HSD likely affects ApoB signaling at both the adipocyte and the glial level." (PMID 39386724, 2024). "Since SREBP-1c inhibits MTTP formation, insulin resistance by overexpressing SREBP-1c contributes to lower apolipoprotein B incorporation and consequent lower VLDL formation." (PMID 39064723, 2024). "Research demonstrated that SHBG levels are closely associated with central obesity, BMI, HDL, apolipoprotein B (apoB) and insulin levels in women, with the strongest correlation being with insulin resistance." (PMID 38892323, 2024). "PCOS patients had significantly higher levels of fasting insulin (FINS), hemostasis of model assessment-insulin resistance, low-lipoprotein cholesterol, triglyceride, apolipoprotein B, apolipoprotein B/apolipoprotein A1, and homocysteine than the controls." (PMID 36930082, 2023).
Insulin resistance (continued). "Higher levels of triglycerides, apolipoprotein B, homeostasis model assessment of insulin resistance, ultrasensitive C-reactive protein, serum amyloid A, and carotid intima-media thickness were observed in the overweight group." (PMID 37341220, 2023). "This has been shown in some studies, where people after cholecystectomy have an increase in fat levels, apolipoprotein B, insulin and in the Homeostatic Model Assessment for Insulin Resistance (HOMA-IR) index." (PMID 37761319, 2023). "Regarding insulin resistance, numerous studies have established correlation between ApoA1, Apo B and ApoA1/ApoB ratio with insulin resistance in both diabetic and normo-glycemic patients." (PMID 37420190, 2023). "The most outstanding cluster was cluster #0 apolipoprotein B, followed by cluster #1 type 2 diabetes, cluster #2 insulin resistance, cluster #3 cardiovascular disease, cluster #4 physical activity, cluster #5 fatty acids, and cluster #6 lipid metabolism." (PMID 37152935, 2023). "Insulin resistance plays an essential role in VLDL metabolism by increasing the availability of apolipoprotein B (ApoB), the primary lipoprotein of VLDL, leading to the increased hepatic synthesis of VLDL." (PMID 36536371, 2022). "ApoB quantification is especially useful in patients with insulin resistance and elevated triglyceride levels above 150 mg/dL, where the Friedewald equation becomes inaccurate and loses its ability to provide a measure of atherogenic load." (PMID 34677405, 2021). "Previous study revealed that ApoB/A1 ratio added significant information for predicting insulin resistance." (PMID 33794863, 2021). "Particle-based measures such as LDL-P or apolipoprotein B (ApoB) are discordantly greater than LDL-C more frequently in patients with insulin resistance, lower HDL-C, lower LDL-C, higher TG, and those on statins." (PMID 35011019, 2021). "Thus, APOA-I and APOB genetic variations may have a causal effect on insulin resistance and MetS." (PMID 33005209, 2020). "Our study was the first to comprehensively examine the roles of APOA-I and APOB levels and their genetic variations on insulin resistance, MetS, and OSA using current large-scale sampling and strict data acquisition." (PMID 33005209, 2020). "Particularly, no current data on potential links between susceptibility genes for APOA-I and APOB and OSA-related insulin resistance and MetS are available." (PMID 33005209, 2020). "Not only did serum APOA-I and APOB levels correlate with insulin resistance and MetS, but cumulative genetic variants of APOA-I and APOB also exhibited effects on insulin resistance and MetS in OSA." (PMID 33005209, 2020). "Our study was the first to screen 42 genetic variants and ultimately combine four APOA-I SNPs and five APOB SNPs (using the GRS model) to comprehensively examine the genetic roles of APOA-I and APOB in insulin resistance and MetS in OSA." (PMID 33005209, 2020). "The relationships between apolipoprotein A-I (APOA-I), apolipoprotein B (APOB) with insulin resistance, metabolic syndrome (MetS) are unclear in OSA." (PMID 33005209, 2020). "Our data indicate that genetic variants of APOA-I and APOB SNPs play different roles in metabolic disorders, such as APOA-I rs9804646 decreased the risk of insulin resistance and MetS, but APOA-I rs888246 increased the risk of insulin resistance and MetS." (PMID 33005209, 2020). "Conversely, increased ApoB secretion and decreased ApoB clearance due to insulin resistance can lead to elevated ApoB levels in the blood and promote the occurrence and development of NAFLD." (PMID 32527258, 2020). "In this study, we pooled multiple genetic variants of APOA-I and APOB to investigate the effects of APOA-I and APOB genotype on insulin resistance and MetS in the large-scale, clinical cohort study on OSA." (PMID 33005209, 2020).
Insulin resistance (continued). "Our study suggests serum APOA-I, APOB level associated insulin resistance and MetS in OSA, and APOA-I and APOB were involved in metabolism and probably further increase cardiovascular disease risk." (PMID 33005209, 2020). "Insulin resistance increases hepatic synthesis of apolipoprotein B (apoB) and triglyceride rich VLDL particles." (PMID 32429441, 2020). "APOB is a lipoprotein whose overproduction is a characteristic of insulin resistance, which can lead to type 2 diabetes." (PMID 31350469, 2019). "Normally, insulin, through PI3K activation, promotes the degradation of apoB, but under insulin resistance this degradation is impaired." (PMID 30170598, 2018). "The ApoB/ApoA-I ratio was closely correlated with other lipid parameters and insulin resistance both in men and women." (PMID 28110289, 2017). "We evaluated other lipid profiles related to insulin resistance and micro-inflammation such as apoB, small dense LDL, RLP-C, and high-sensitivity CRP (hsCRP)." (PMID 28646901, 2017). "Insulin resistance prompts hepatic overproduction of apoB and VLDL and, eventually, to hypertriglyceridemia." (PMID 27200421, 2016). "This type of consideration thus alludes to biomarkers such as ApoB and insulin resistance that are potentially more important for lifestyle and pharmaceutical interventions." (PMID 25774201, 2015). "Meanwhile, progressive insulin resistance has been linked to significantly reduced microsomal triglyceride transfer protein (MTP) expression, a protein that facilitates apoB maturation, thus impairing VLDL secretion." (PMID 24454851, 2014). "The ApoB/ApoA-I ratio was an independent predictor of insulin resistance after adjustment for age and race and remained significant after further adjustment for MetS components and traditional and inflammatory risk factors." (PMID 24949011, 2014). "ApoB showed positive correlation with insulin resistance, but ApoA1, ApoA1/ApoB, LDL-C/ApoB, and HDL-C/ApoA1 revealed inverse results in non-diabetic normoglycemic patients." (PMID 24093822, 2013). "Type 2 diabetes is characterize through the increasing in insulin resistance, plasma triglyceride, apoB, homocysteine and decreasing in apoA-I and HDL-C." (PMID 24250489, 2012). "Among men, factors were age, apolipoprotein A1 level, apolipoprotein B level, and insulin resistance." (PMID 21159215, 2011). "Overall, SAD showed a slightly higher correlation with most cardiovascular risk factors, especially insulin resistance, insulin, CRP, apolipoprotein B and triglycerides (all P-values < 0.01) than other anthropometric measures." (PMID 17391519, 2007). "In the state of insulin resistance, ApoB degradation is inhibited, leading to an overproduction of very low-density lipoproteins (VLDL), which results in the predominance of sdLDL due to increased activity of cholesteryl ester transfer protein and hepatic lipases." (PMID 40309448, 2025). "We identified studies with robust evidence for causal associations between genetically predicted LDL cholesterol, HDL cholesterol, triglycerides, apolipoprotein B, blood pressure, type 2 diabetes, and glycemic traits such as HbA1c and insulin resistance with CAD and stroke." (PMID 37804188, 2023). "One most recently published retrospective study on 700 Chinese women indicated that most of these subjects had low HDL-C; that subjects with clinical hyperandrogenism also had lower ApoA levels; and that the levels of TG, LDL-C, and ApoB were increased in women with PCOS with insulin resistance." (PMID 36980195, 2023). "Furthermore, insulin resistance in these patients contributes to the increased production of chylomicrons, mainly due to the increased synthesis and secretion of apolipoprotein B48 (apoB48)-containing lipids and lipoproteins by the intestines." (PMID 36430292, 2022).